HOXB3 (homeobox B3)
Diseases named in the same sentence as HOXB3 in open-access papers (continued):
Sharing a sentence is not in itself a finding about the gene and the disease.
lung adenocarcinoma (2 papers, 2018 to 2019). A carcinoma that arises from the lung and is characterized by the presence of malignant glandular epithelial cells. "HOXB3 increases the expression of DNA methyltransferase (DNMT3B), which is in turn recruited to the RASSF1A promoter, resulting in hypermethylation and silencing of RASSF1A expression in lung adenocarcinoma." (PMID 29439669, 2018).
triple-negative breast carcinoma (2 papers, 2020 to 2021). An invasive breast carcinoma which is negative for expression of estrogen receptor (ER), progesterone receptor (PR), and human epidermal growth factor receptor 2 (HER2). "Some studies show that high expression of the SETD3 gene is associated with poor survival in triple-negative breast cancer, while HOXB3 and FOXA1 were identified as indicators of better prognosis." (PMID 34416858, 2021).
AIDS (1 paper, 2024). A syndrome resulting from the acquired deficiency of cellular immunity caused by the human immunodeficiency virus (HIV). "We present that in HIV infection, miRNA-mediated post-transcriptional dysregulation of HOXB3 mRNA inhibits multi-lineage hematopoiesis, which translates into hematological disorders in virus-infected patients with HIV/AIDS." (PMID 38721526, 2024).
Alzheimer disease (1 paper, 2023). A progressive, neurodegenerative disease characterized by loss of function and death of nerve cells in several areas of the brain leading to loss of cognitive function such as memory and language. "Worth a mention is the downregulation of DDIT3, SMC4, and TENM4 in replicative senescence of human fibroblasts; the upregulation of SMC4 and MCM7 after vitamin C treatment; the upregulation of HOXB3 and TENM4 in Alzheimer’s disease; and the deregulation of DDIT3 and SMC4 in COVID-19 disease." (PMID 36982191, 2023).
Arboleda-Tham Syndrome (1 paper, 2022). "The first and second DMRs overlap regions of HOXB2, HOXB3 and HOXB4 and is hypomethylated in Arboleda-Tham Syndrome patients relative to controls." (PMID 36064314, 2022).
autoimmune disease (1 paper, 2020). A disorder resulting from loss of function or tissue destruction of an organ or multiple organs, arising from humoral or cellular immune responses of the individual to their own tissue constituents. "Previous studies have suggested that HOXB3, GH1 and KIR2DL4 are involved in autoimmune disease such as Thyroid-associated orbitopathy (TAO), Type 1 diabetes (T1DM), and Systemic lupus erythematosus (SLE)." (PMID 33384687, 2020).
autosomal dominant polycystic kidney disease (1 paper, 2021). Autosomal dominant form of polycystic kidney disease. "Expression of the lncRNA Hoxb3os (homeobox B3 and homeobox B2, opposite strand) is significantly decreased in the renal tissues of patients with autosomal dominant polycystic kidney disease (ADPKD) and in a mouse model of ADPKD." (PMID 33681192, 2021).
bladder cancer (1 paper, 2020). "Among these identified genes, 5 genes (CALD1, HOXB3, HOXB6, MOGAT2, and TNC) have been reported to be associated with the development or prognosis of bladder cancer, indicating that the results in our study are consistent with previous publications in bladder cancer." (PMID 33204728, 2020).
brain cancer (1 paper, 2020). A primary or metastatic malignant neoplasm affecting the brain. "Notably, there were 6 HOX genes, namely HOXA2, HOXA4, HOXB2, HOXB3, HOXB4, and HOXC4, which changed expression only in brain cancer (either in GBM, brain lower grade glioma (LGG), or in both)." (PMID 32545894, 2020).
breast tumors (1 paper, 2020). "Through the enrichment analysis of multiple pathways, we screened for possible mechanisms for the HOXB3 gene to play a role in breast tumors." (PMID 33240685, 2020).
craniofacial clefts (1 paper, 2022). "Some of these proteins like Homeobox Protein BarH-like 1 (BARX1), Distal-Less Homeobox 4 (DLX4), Forkhead Box E1 (FOXE1), Homeobox Protein Hox-B3 (HOXB3), and Muscle Segment Homeobox 2 (MSX2) have been associated with the formation of craniofacial clefts." (PMID 37733420, 2022).
gastric cancer (1 paper, 2021). A primary or metastatic malignant neoplasm involving the stomach. "To demonstrate the CeTF package application, we analyzed gastric cancer RNA-seq data obtained from TCGA (The Cancer Genome Atlas) and found the HOXB3 gene as the second most relevant TFs with a high regulatory impact (TFs-HRi) regulating gene pathways in the cell cycle." (PMID 34416858, 2021).
HIV-1 infection (1 paper, 2024). The type species of lentivirus and the etiologic agent of acquired immunodeficiency syndrome (AIDS). "Furthermore, herein we show that HIV-1 infection caused changes in microRNA that disrupt homeobox HOXB3 versus control GAPDH messenger RNA, with the consequences of inhibiting hematopoiesis due to the loss of HOXB3 messenger RNA expression." (PMID 38721526, 2024).
invasive carcinoma (1 paper, 2024). A carcinoma that is not confined to the epithelium, and has spread to the surrounding stroma. "In the present study, we demonstrated upregulation of HOXB3 in invasive carcinoma compared to associated IPMN." (PMID 39660530, 2024). "HOXB3 therefore may be a specific marker for high‐grade dysplasia only, the expression of which, if biphasic, could be increased on progression to invasive carcinoma." (PMID 39660530, 2024).
lung carcinoma (1 paper, 2018). "Although other members of the HOX gene family, such as HOXA5, HOXA10, HOXB3, HOXB4, and HOXC618,19, have been found to be overexpressed in lung cancer tissues compared with normal tissues, little is known about the expression and biological function of HOXA4 in lung cancer." (PMID 29700285, 2018).
melanoma (1 paper, 2009). A malignant, usually aggressive tumor composed of atypical, neoplastic melanocytes. "Moreover, HoxB3 promotes capillary morphogenesis during angiogenesis, and HoxB7 directly upregulates the expression of bFGF in human melanoma cells; the activation of bFGF induces EC proliferation in vitro." (PMID 19825192, 2009).
meningioma (1 paper, 2013). A generally slow growing tumor attached to the dura mater. "Homeobox protein Hox-B3 (HOXB3), LIM domain only protein 3 (LMO3), Homeobox protein Hox-B6 (HOXB6), Homeobox protein Hox-A3 (HOXA3) and DNA-binding protein inhibitor ID-2 (ID2) showed higher under-expression in benignB with respect benignA meningiomas with a fold change lower than −3." (PMID 23840654, 2013).
migraine (1 paper, 2021). "For instance, we identified a new region associated with migraine at 17q21 and our DEPICT gene analysis prioritized three members of the Antp homeobox family genes (i.e., HOXB2, HOXB3, and HOXB6) at this region that encode proteins with a homeobox DNA-binding domain." (PMID 34294844, 2021).
multiple sclerosis (1 paper, 2024). A progressive autoimmune disorder affecting the central nervous system resulting in demyelination. "The remaining genes included MMP2, a modulator of neuronal precursor activity and cognitive and motor behaviors; CFB, a complement factor altered in neurologic diseases such as multiple sclerosis; and HOXB3, a critical choreographer of neural development." (PMID 38376950, 2024).
myeloproliferative neoplasm (1 paper, 2023). A clonal hematopoietic stem cell disorder, characterized by proliferation in the bone marrow of one or more of the myeloid (i.e., granulocytic, erythroid, megakaryocytic, and mast cell) lineages. "Furthermore, HOXB3 whose overexpression is associated with myeloproliferative neoplasm (MPN) disorders recruits DNMT3B to bind in the pre-miR-375 promoter." (PMID 37345170, 2023).
osteoarthritis (1 paper, 2021). A noninflammatory degenerative joint disease occurring chiefly in older persons, characterized by degeneration of the articular cartilage, hypertrophy of bone at the margins and changes in the synovial membrane. "The HoxB3 was identified as a potential biomarker for osteoarthritis and might be used for the prediction of clinically isolated syndrome progress to relapsing-remitting multiple sclerosis." (PMID 35076557, 2021).
Parkinson disease (1 paper, 2021). A progressive degenerative disorder of the central nervous system characterized by loss of dopamine producing neurons in the substantia nigra and the presence of Lewy bodies in the substantia nigra and locus coeruleus. "The aberrant expression of HoxB3 might promote Parkinson’s disease via dysregulating sphingolipid and glutathione metabolism." (PMID 35076557, 2021).
renal cell carcinoma (1 paper, 2021). "We discovered that the mRNA levels of HOXB1/6/8/9 were significantly downregulated in renal cell carcinoma, while HOXB3/4/7 were upregulated in almost all tumors, including RCC." (PMID 34306077, 2021). "In this study, we analyzed the mRNA levels of HOXBs in tumors and normal tissue and found that the mRNA levels of HOXB1/6/8/9 are significantly downregulated in renal cell carcinoma, while those of HOXB3/4/7 are upregulated in nearly all the tumors, including renal cell carcinoma." (PMID 34306077, 2021).
tumor (25 papers, 2011 to 2025). "In this study, higher WNT3A was detected in HOXB3 + tumors and was associated with higher tumor grade and stage." (PMID 36973255, 2023). "Our data in clinical cohorts established that M/H nuclear staining of HOXB3 is associated with tumor progression and poor outcome in abiraterone-treated mCRPC patients." (PMID 36973255, 2023). "As one of the typical HOX protein, HOXB3 has been proven to be associated with tumor progression in hepatocellular carcinoma and breast cancer." (PMID 36973255, 2023). "Altogether, these results indicated HOXB3 drove WNT-associated tumor progression and abiraterone resistance in CRPC xenograft, and antiandrogen combined with HOXB3 suppression could be potential therapy for CRPC with WNT-pathway activation." (PMID 36973255, 2023). "High levels of TILs have been associated with increased patient prognosis, therefore suggesting that HOXB3 mediates tumor immunity in LUAD." (PMID 39858044, 2025). "Regulators associated with tumorigenesis and tumor progression, such as EGR1, FOSL, BATF, and HOXB3, were enriched in malignant clusters." (PMID 39872221, 2025). "To research the function of HOXB3 activation in APC-suppressed tumors (one type of WNT-ON tumor), we introduced a doxycycline-inducible shRNA targeting HOXB3 (Tet-off) into the LNCaP-AI cells with APC knockdown (LAPCi-HOXB3Tet for short)." (PMID 36973255, 2023). "Our previous findings in hormone-naive local PCA indicated that HOXB3 mRNA expression correlated with tumor grade,stage and tumor recurrence after radical prostatectomy." (PMID 36973255, 2023). "We can see, the most significant tumor inhibition was observed in group with HOXB3 knockdown and abiraterone treatment." (PMID 36973255, 2023). "In the whole course of the experiment, HOXB3 remained upregulated in tumor tissues, as confirmed by qRT-PCR of HOXB3 mRNA in harvested tumors." (PMID 36973255, 2023). "The same study also found a difference in HOX gene expression between platinum sensitive and resistant tumours in paired cell lines, with the resistant tumours showing a higher expression of HOXB3, B4 and B9." (PMID 31382546, 2019). "Phenotypic effects of miR-375 overexpression and HOXB3 knockdown were assessed using viability (trypan blue exclusion assay), colony formation/replating, as well as tumor xenograft assays in vivo." (PMID 29439669, 2018). "The downregulation of tumor suppressors PAX5 and HOXB3 by CRE mutations in MM is entirely consistent with their decreased expression contributing to development and progression of MM as is the case with other B-cell malignancies." (PMID 29654271, 2018). "Some studies suggested that loss of HOXB3 correlates with the development of hormone receptor negative breast cancer, or act as tumor suppressors through FLT3-ITD driver in AML." (PMID 38254070, 2024). "In addition, levels of HOXB3 mRNA were evaluated by qRT-PCR at the end of this experiment, showing that HOXB3 remained suppressed in HOXB3-OFF tumor tissues." (PMID 36973255, 2023). "Overexpressed HOXB3 in various cancers promotes tumor progression." (PMID 34187591, 2021). "However, abiraterone and HOXB3 suppression could significantly decrease the proliferation of WNT-ON CRPC tumor." (PMID 36973255, 2023). "Together, our data indicate that HOXB3 protein is demonstrated to be alternatively transcriptive effector of WNT signaling that is responsible for tumor progression in WNT-activated CRPC and may serve as a potential therapeutic target for the subgroup of patients." (PMID 36973255, 2023). "Different from HOXB3, HOXB5 was negatively correlated with myeloid cell differentiation signaling, but promoted tumor aggression and progression of various tumors including AML." (PMID 38254070, 2024).
tumor (continued). "Consistent with the proliferation of tumor cells, PSA levels significantly increased in medium cultured HOXB3-overexpressed cells." (PMID 36973255, 2023). "We analyzed the correlation between HOXB3 and TNM stage and tumor size of clinically collected HCC patients, and patients with high HOXB3 expression had advanced tumor stage." (PMID 35127344, 2022). "We found that, in addition to interacting with CD2, CD58 was co-expressed and physically interacted with HOXB family genes (HOXB2, HOXB3, and HOXB5), AKAP12, CLIC1, CPNE3, etc., which were reported to be involved in tumor initiation and progression." (PMID 34193136, 2021). "A negative correlation was exhibited between HOXB3 and the quantity of tumor-infiltrating lymphocytes (TILs) and tumor immune stimulators." (PMID 39858044, 2025). "In silico analysis indicated that HOXB3 was significantly upregulated in LUAD tumors when compared to normal tissue and was a risk factor for decreased survival regardless of tumor stage." (PMID 39858044, 2025). "Additional HOXB3 had no influence on testosterone generation and AR-target genes expression in tumor cells." (PMID 36973255, 2023). "Together, these results indicated HOXB3 drove CRPC tumor growth and abiraterone resistance independent of A/AR signaling." (PMID 36973255, 2023). "The growth rates of HOXB3-ON xenografts were reduced by abiraterone or doxycycline-induced HOXB3-konckdown, however, tumor progressions never stopped in the two groups (black and crimson)." (PMID 36973255, 2023). "Similarly, 45/49 and 36/48 LAC cases compared to 3/31 and 0/31 tumor-adjacent normal lung samples showed hypermethylation of the SIM1 and HOXB3/HOXB4 regions, respectively." (PMID 27782156, 2016). "To uncover the mechanism of HOXB3 driving tumor progression, we performed RNA-sequencing in HOXB3 negative (HOXB3-) and HOXB3 high (HOXB3 + ) staining CRPC tumors and determined that HOXB3 activation was associated with the expression of WNT3A and enriched WNT pathway genes." (PMID 36973255, 2023). "Nevertheless, though we did detect significant increases of tumor suppressing microRNAs, miR-28 and miR-34a, their respective targets, HoxB3 and KIT, were not decreased, implying that miR-28-HoxB3 and miR-34a-KIT axes may not involve in the anti-CRC activities of Res." (PMID 26674205, 2015).
cancer (21 papers, 2012 to 2025). A tumor composed of atypical neoplastic, often pleomorphic cells that invade other tissues. "What’s more, HOXB3 knockdown in LNCaP-AI and hCAF (human cancer-associated fibroblasts) cells didn’t change WNT3A expression (data not shown)." (PMID 36973255, 2023). "Studies have shown that the HOXB gene cluster contributes to cancer development; increased expression of HOXB3, HOXB6, HOXB7, HOXB8, and HOXB9 in LUAD patients is linked with poor overall survival (OS)." (PMID 36506331, 2022). "- TIMER: we used the “Correlation” module to analyze the correlation between HOXB3 expression and the target genes, and we explored the association of immune infiltration levels among cancers with different SCNAs affecting HOXB3 expression in the “SCNA” module." (PMID 33240685, 2020). "Other studies have demonstrated that HOXB3 promotes cancer cell migration and progression when upregulated." (PMID 39851503, 2025). "HOXB3 expression plays a role in maintaining tissue homeostasis, and multiple studies have shown that its silencing can lead to a less aggressive cancer cell phenotype by restoring epithelial characteristics." (PMID 38553466, 2024). "Despite the absence of articles on HOXB3 and HCC progression, many studies have correlated HOXB3 with other types of cancers." (PMID 35127344, 2022). "HOXB3 has been described affecting the proliferation of different cell lineages with research mainly focused on HOXB3 role in development of different cancer types and formation of metastases." (PMID 33917041, 2021). "In recent years, immunotherapy has been a hot topic in cancer research, therefore we investigated the relationship between HOXB3 expression and representative immune markers of several immune cells." (PMID 33240685, 2020). "As a transcript factor, HOXB3 contributes to cancer cell proliferation and metastasis through activating DNA methyltransferase (DNMT3B) and subsequent inactivation of the RASSF1A tumor suppressor gene." (PMID 29439669, 2018). "Also upregulated was homeobox B3 (HOXB3, Log2FC = 7.88), a member of the HOX gene family, which is linked to embryonic development, as well as the progression of diseases and cancers." (PMID 40052144, 2025). "HOXB3 has different effects in promoting or suppressing cancer in different types of tumors." (PMID 33240685, 2020). "On the contrary, there are also some genes, such as HOXB3, HOXD1, HOXC9, and HOXA13, that are highly expressed in some cancers and have better OS (p<0.05)." (PMID 39980564, 2025). "Palakurthy has shown that DNMT3B is the target of HOXB3 protein and is involved in the epigenetic regulation of tumor suppressor gene RASSF1A in lung adenocarcinoma and other cancers." (PMID 34722321, 2021). "Among them were five genes with known transcription factor activity (PBX3, HOXB3, LEF1, HOXA7, LBH) and three genes with oncogenic potential (PAPD7, PBX3, LEF1) for which a role in other cancers has been suggested previously." (PMID 32728112, 2020). "The results showed that some HOX genes in pan-cancer had significant strong correlation (R≥0.8): HOXA9 with HOXA10, HOXB5 with HOXB6 and HOXB8, HOXB8 with HOXB6 and HOXB9, HOXB3 with HOXB4 and HOXB5 and HOXB6, HOXC8 with HOXC9, HOXC9 with HOXC10, HOXD10 with HOXD11." (PMID 39980564, 2025).
metabolic disorders (1 paper, 2021). "Consistently, the results revealed that dysregulation of MAG, HOXB3, MYRF and PLP1 led to metabolic disorders of sphingolipid and glutathione, which contributed to the pathogenesis of PD." (PMID 33325158, 2021).
prostate (1 paper, 2017). "Furthermore, HOXB3 mRNA and protein are over-expressed in primary PC tissues compared to the adjacent normal prostate tissues, which suggests a potential role of HOX on prostate carcinogenesis." (PMID 27819754, 2017).
HOXB3 also shares sentences with these, for which no sentence is quoted: hematological disorders (2 papers); acute leukemia (1); cleft palate (1); colorectal cancer (1); craniosynostosis (1); dementia (1); embryonal carcinoma (1); endometrial cancer (1); familial prostate cancer (1); hepatocellular carcinoma (1); Huntington disease (1); motion sickness (1); myelodysplastic syndrome (1); neurologic diseases (1); Obesity (1); orofacial cleft (1); Primary hypothyroidism (1); relapsing-remitting multiple sclerosis (1); systemic lupus erythematosus (1).